IL6 (interleukin 6)
Diseases named in the same sentence as IL6 in open-access papers (continued):
Sharing a sentence is not in itself a finding about the gene and the disease.
Sepsis (continued). "After sepsis, systemic levels of C-reactive protein (CRP) and soluble programmed death ligand 1 (a marker of immunosuppression) are elevated for up to one year in patients while interleukin 6 (IL6) and IL10 persists for several months in human and experimental models." (PMID 33969227, 2020). "We here demonstrate that blood leukocytes of hospitalized CAP patients display an impaired release of TNF-α, IL-1β, IL-6, and IL-10 as well as an heightened production of IL-1RA in response to stimulation with LPS and K. pneumoniae, regardless of the presence of sepsis." (PMID 32477337, 2020). "Multiple linear regression analysis was employed to evaluate the relationship between SOFA scores and confounding factors that may be related to the severity of sepsis, including miR-223, age, lymphocyte counts, monocyte counts, white blood cell (WBC) counts, PCT, CRP, IL-6, and D-dimer." (PMID 33077816, 2020). "The authors concluded that IL-6 could aid in confirming, rather than excluding, sepsis, owing to the relatively high specificity." (PMID 33198109, 2020). "However, the specific mechanism by which ADAR1 reduces IL-6 expression and alleviates sepsis is not clear." (PMID 32273831, 2020). "Also, acupuncture therapies were reported as being capable of decreasing secretion of IL-6, high mobility group protein box-1 (HMGB1), TNF-α, IL-10, and interferon-γ (IFN-γ), demonstrating acupuncture at ST36's potential of reducing inflammation in sepsis." (PMID 32215037, 2020). "Collectively, a dramatic increase in IL-6 secondary to sepsis or other pathological processes rather than the initial viral infection may aggravate severe inflammation and lead to fatal consequences." (PMID 32917983, 2020). "This could be explained by the fact that sepsis induces eCIRP release into the lungs, which activates ATII cells to release cytokines and chemokines, such as IL-6 and CXCL2, resulting in a subsequent infiltration of neutrophils into the lung tissue causing ALI." (PMID 32984356, 2020). "Conversely, IL-6 remained unchanged in patients without sepsis throughout this study." (PMID 32635454, 2020). "We confirmed the reasonable high sensitivity of ITQ and IL-6 at the time of diagnosis, indicating that biomarkers indeed may help to rule out neonatal and young infant sepsis and thereby help to reduce the well-described antibiotic overuse in this age group." (PMID 32447562, 2020). "Importantly, IL-6 is one of the highest circulating cytokines expressed in patients with sepsis-induced DIC, and it is considered an early predictor of DIC in patients with sepsis." (PMID 32655577, 2020). "IL-6 has a prognostic role in differentiating patients with sepsis from those without sepsis." (PMID 32635454, 2020). "A significant decrease of IL-6 levels could be achieved in patients with sepsis, however, without a mortality benefit." (PMID 33141843, 2020). "Analyzing the results of sepsis markers revealed that the median procalcitonin (PCT) level of all the studied neonates was 10.4 ng/ml and the range was (0.1–50.6) ng/ml, median CRP serum level was 48 mg/dl and ranged 4–140 mg/dl and IL-6 ranged from 5–120.8 pg/ml with median serum level 36.1 pg/ml." (PMID 33061986, 2020). "NLRP3-immunocompromised septic patients who survived and recovered from sepsis (n = 3) did not have detectable levels of IL-6 in their plasma at 120 days after the septic episode, but their NLRP3 inflammasome could be activated normally." (PMID 31221993, 2019). "Among these models, sepsis-AKI had the least severe renal injury (increased BUN and Scr) with the most severe liver injury (increased ALT and changes in liver histopathology), the most severe intestinal leakage (increased serum (1→3)-β-D-glucan) and the highest increase in serum IL-6." (PMID 30991873, 2019).
Sepsis (continued). "Plasma ferritin, IL-6, sTfR/log ferritin and the RDW had lower AUCs than the SOFA score (all P < 0.05) but plasma hepcidin had an AUC similar to the SOFA score, which suggested its similarity to the SOFA score for predicting the 28-day mortality of patients with sepsis." (PMID 31183575, 2019). "In a murine model of sepsis induced by caecal ligation and puncture, DHA-derived resolvin D1 decreased the bacterial load in the blood and peritoneum, decreased lung injury, decreased plasma concentrations of TNF, IL-6, IL-10, and interferon-γ, and improved survival." (PMID 31072006, 2019). "High serum IL-6 in sepsis might also influence an expression of CYP3A11 as demonstrated by the correlation between CYP3A11 and serum IL-6 in sepsis-AKI model together with in vitro IL-6 enhanced CYP3A11 expression on HepG2 cells." (PMID 30991873, 2019). "However, similar to CRP and PCT, IL-6 concentrations were also elevated in non-septic disease states, limiting its specificity for the assessment of sepsis in patients with critical illness." (PMID 31569348, 2019). "Interestingly, significant differences were seen in plasma IL6 in individuals with or without rs7038903 C allele (28pg/ml (IQR 12-86) vs 90pg/ml (IQR 49-155); (p = 0.022) in patients with severe sepsis in the Malay ethnic group." (PMID 31097890, 2019). "Biomarkers of inflammation and sepsis investigated in foals and adult horses include lactate, soluble CD14 (sCD14), serum amyloid A, procalcitonin, C-reactive protein (CRP), haptoglobin (Hp), interleukin 1β (IL-1β), interleukin-10 (IL-10), and interleukin-6 (IL-6)." (PMID 30931316, 2019). "This study investigated the clinical value of interleukin-6 (IL-6), pentraxin 3 (PTX3), and procalcitonin (PCT) in patients with sepsis and septic shock diagnosed according to the Third International Consensus Definitions for Sepsis and Septic Shock (Sepsis-3)." (PMID 31718563, 2019). "Similarly, infants with sepsis, defined by elevated systemic markers of inflammation (IL-6 and/or CRP) and the use of antibiotics, showed a non-significant trend toward lower platelet counts before initiation of therapy." (PMID 29564323, 2018). "Their use in qualifying critically ill patients at nutritional risk has been extensively evaluated, although not in studies of patients with sepsis, when interleukin 6 levels, which are not included in the modified NUTRIC score, may be elevated." (PMID 30018224, 2018). "The levels of IL-6, TNF-α, and HSP70 decreased within the first 12 h of CVVH in AKI patients with sepsis, whereas the levels of DAMPs at the outlet were temporarily increased after blood passage from the inlet through the dialyzer in survivor AKI patients with sepsis." (PMID 30666251, 2018). "IL-6 governs the production of acute phase proteins, and together with IL-1β, IL-12/23/p40, and TNF-α, are termed proinflammatory cytokines and are induced in intestinal mucosa during sepsis, and in enterocytes after in vitro treatment with endotoxin and other proinflammatory cytokines." (PMID 29491864, 2018). "In patients with sepsis, serum tenascin-C levels were significantly positively correlated with SOFA scores (P = 0.011), serum creatinine (P = 0.006), C-reactive protein (CRP) (P = 0.001), interleukin-6 (IL-6) (P < 0.001), and tumor necrosis factor α (TNF-α) (P = 0.026)." (PMID 30442110, 2018). "During sepsis, endotoxin lipopolysaccharides (LPS) activate toll-like receptor 4 (TLR4) signaling pathway and further induce translocation of nuclear factor-kappa B (NF-kappa B) to modulate expression of pro-inflammatory genes, including TNF-α, IL-6, and IL-1β." (PMID 30083155, 2018). "One possible reason for the absence of changes in IL‐6 levels may be related to the fact that we have excluded neonates with confirmed or suspected sepsis, while, in other studies, babies with sepsis were included." (PMID 28553016, 2017). "However, serum concentrations of inflammatory cytokine IL-6 and TNF-α during sepsis were similar." (PMID 28976973, 2017).
Sepsis (continued). "Several studies demonstrate that the protective role of MSCs in sepsis may be attributed to the soluble paracrine factors released by these cells, such as interleukin (IL)-10, prostaglandin E2 (PGE2), tumor necrosis factor (TNF)-α and IL-6." (PMID 29273091, 2017). "Moreover, among sepsis patients, the rs1024611 AG/GG and rs2857656 GC/CC carriers exhibited significant increases in expression levels of MCP-1 (P = 0.025), TNF-α (P = 0.034) and IL-6 (P = 0.043) compared with the rs1024611 AA or rs2857656 GG carriers." (PMID 28472164, 2017). "In ONX 0914 treated mice we found elevated serum levels of creatinine and urea on day 7 and of TNF-α and IL-6 on day 3 and day 7 (data not shown) indicating that renal failure and sepsis might occur faster upon LMP7 inhibition." (PMID 26776888, 2016). "As human IL-6 levels are indicative of chances of survival during sepsis, a patient-centered decision on whether or not to administer antibodies to IL-6 is mandatory based upon a broader patient’s immunological profile." (PMID 27044016, 2016). "The aim of this study was to determine the impact of surgical interventions on the novel sepsis biomarker soluble urokinase plasminogen activator receptor (suPAR) and to compare with the routinely used laboratory parameters CRP, PCT, and IL-6 in patients with culture-proven bloodstream infection." (PMID 30671318, 2016). "Studies attempting to elucidate the hypothermic response in sepsis have focused on a hypothesized lack of proinflammatory cytokines, in particular interleukin (IL)-6 and tumor necrosis factor (TNF)-α, which are the main mediators of fever." (PMID 27737683, 2016). "Also, lower circulating levels of IL-6 have been found in CC homozygous patients with sepsis and other non-infectious diseases." (PMID 27834822, 2016). "Meanwhile, during sepsis, plasma NGAL was moderately to strongly correlated with cytokine interleukin (IL)-6 in septic patients and animal models, which clarified that plasma NGAL might be involved in immune responses during inflammation, rather than only restricted to the diagnosis of AKI." (PMID 26880194, 2016). "Therefore, miR-23b may play a significant role in the pathogenesis and progression of sepsis by inhibiting the expression of inflammatory factors, including NF-κB, TNF-α, IL-6, ICAM-1, E-selectin and VCAM-1." (PMID 25780398, 2015). "Notably, in the ongoing sepsis of nonsurvivors (day 7), IL-6 did not significantly decrease in plasma, enabling the autocrine activation of IDO via the AhR-IL-6-STAT3 loop as described in human cells." (PMID 26881062, 2015). "The postconditioning of sevoflurane by various doses (0%, 1%, 3%, or 7%) for 1 hour in in vitro sepsis environment leads to an increase of cell viability and decrease of inflammatory indicators such as toll-like receptor (TLR) 2, toll-like receptor (TLR) 4, and cytokines, such as TNF-α and IL-6." (PMID 26101769, 2015). "Similarly, PCT the most widely utilized “new generation” biomarker that, especially in combination with additional inflammatory markers such as IL6 and CRP, is reported in some studies as having a good predictive value for sepsis, was temporarily increased after surgery in both groups." (PMID 26263001, 2015). "In addition to attenuating the abrupt release of pro-inflammatory cytokines, including TNF-α, IL-1β and IL-6, treatment with chlorogenic acid enhanced serum Th1 cytokines during the late phase of sepsis without affecting Th2 cytokine release." (PMID 26063084, 2015). "We speculate that proinflammatory cytokines such as TNF-α, IL-1β, and IL-6 were released in the early stage of ALI challenge; in other studies, IL-6 was considered a particularly useful marker for prediction of the severity of sepsis." (PMID 25022445, 2014).
Sepsis (continued). "Additionally, two hours after sepsis, the CLP model had the greatest gene expression related to NFκB signaling, TLR signaling, acute phase response and Il-6 signaling, whereas one and three days after sepsis, the the it actually showed inhibition of many of these inflammatory pathways." (PMID 24788351, 2014). "In addition, although there was extraordinary high amounts of IL-6, which was deemed as prototypical cytokine for endotoxemia and sepsis studies, around 3–12 h, there was no statistically significant change at 24 h." (PMID 24618279, 2014). "The study of proinflammatory cytokines IL-6, TNF-α, IL-1β, and IL-8 and anti-inflammatory cytokines IL-10 and TGF-β as reliable biomarkers of neonatal infection has been shown to be potentially useful for early sepsis diagnosis and to predict the severity of disease at early stages of the infection." (PMID 25614712, 2014). "The sepsis-induced increase in IL-6 was not changed by treatment with atenolol." (PMID 25413250, 2014). "Inflammatory mediators, such as tumor necrosis factor- (TNF-) α, interleukin- (IL-) 1, IL-6, interferon- (IFN-) γ, IL-8, nitric oxide (NO), and reactive oxygen species (ROS), are released from liver resident and infiltrated immune cells, which mediate sepsis-induced liver injury." (PMID 25525303, 2014). "In addition, TNF-α and IL-1 amplify inflammatory cascades in an autocrine and paracrine manner by activating macrophages to secrete other proinflammatory cytokines (IL-6, IL-8, and MIF), lipid mediators, and reactive oxygen and nitrogen species, leading to sepsis-induced organ dysfunction." (PMID 23853427, 2013). "Results of our study afforded scientific evidence for BHT in treating sepsis by a CLP model and its effects on cytokine modulation: early administration of high-dose BHT markedly improved survival by directly reducing plasma level of IL-6, and simultaneously decreased IL-10 was observed." (PMID 23762108, 2013). "Plasma IL-6 level in survivors with severe sepsis was lower than that in non-survivors." (PMID 23670410, 2013). "IL-6 serum level was shown to be correlated directly with levels of PCT in the patients of uncertain sepsis and without sepsis in our population; however, this was not significantly different between another two groups of clinical and positive blood culture sepsis." (PMID 22708043, 2012). "Sensitivity, specificity, positive predictive value (PPV), negative predictive value (NPV) for D3–4/D1–2 mHLA-DR, D1–2 IL-6 concentration, and the combination of D3–4/D1–2 mHLA-DR and D1–2 IL-6 concentration, for the diagnosis of sepsis during the intensive care unit (ICU) stay." (PMID 22431998, 2012). "The underlying mechanisms by which MBC extract conferred protection against lethal sepsis are complex, but may be attributable to the inhibition of endotoxin-induced release of HMGB1, IL-6, and several chemokines (including MCP-2, MCP-3, RANTES, GRO, and I-309)." (PMID 23193422, 2012). "PRISM scores and IL-6 levels for shock non-survivors were significantly higher than those for both groups of survivors (P < 0.001), and those for shock survivors were significantly higher than those for sepsis survivors (P < 0.001)." (PMID 21276273, 2011). "Hence, circulating levels of procalcitonin, C-reactive protein, interleukin (IL)-1, IL-6, IL-8, IL-10, tumor necrosis factor alpha (TNF-α), Fas-ligand, and monocyte chemoattractant protein 1 (MCP-1) have all been highlighted as potential markers of sepsis." (PMID 22220196, 2011). "We studied the usefulness of serum procalcitonin (PCT), interleukin-6 (IL-6), lipopolysaccharide binding protein (LBP) levels and C-reactive protein (CRP) levels, in differentiating between systemic inflammatory response syndrome (SIRS) and sepsis in critically ill patients." (PMID 21687569, 2011).
Sepsis (continued). "Interestingly, 1 sepsis and 3 ARDS patients had relatively high titer autoantibodies against IL-6 and/or INF-ω suggesting that these autoantibodies might have a role in dampening the activity of these cytokines." (PMID 20946647, 2010). "Thus, for future studies, measurements of plasma PCT concentrations may be a helpful approach to improve the outcome prediction in patients with severe sepsis particularly when combined with the APACHE II scoring system and IL-6 measurement." (PMID 22615611, 2010). "Thus, thromboelastometry lysis index and procalcitonin, but not interleukin 6 and C-reactive protein, are capable of detecting patients with severe sepsis in critically ill adults." (PMID 20929576, 2010). "Also, the chemokines, CCL-2, CXCL-2, and cytokines, IL-1β and IL-6, were not affected by NK-2R blocking in sepsis." (PMID 21188216, 2010). "LBP, IL-6 and CRP levels were significantly higher among sepsis patients compared with infected children without SIRS (p < 0.001) and were significantly higher in the severe sepsis group compared with the less severe sepsis group (p < 0.001 for all differences)." (PMID 20158885, 2010). "Furthermore, IL-6 levels are not indicators of infections or sepsis, although they correlate well with the degree of severity of inflammation." (PMID 19493352, 2009). "Levels were higher in sepsis than in non-sepsis patients with a clear association to markers of the inflammatory response including white blood cell count, CRP, procalcitonin, and with the proinflammatory cytokines IL-6, IL-10, and TNF-α." (PMID 19545363, 2009). "In contrast to ELISA results, sepsis PBMC did not increase IL-6 at the mRNA level." (PMID 18053242, 2007). "Nonetheless, there appeared to be differences in the pattern of cytokine concentrations related both to the presence or absence of sepsis and to the nutritional management of the animals, with recovery of circulating IL-6 and IL-10 being more frequent in animals with sepsis administered PN." (PMID 17634149, 2007). "However, coculture of PBMC derived from sepsis patients with PSC did not alter IL-6 levels (p = 0.1)." (PMID 18053242, 2007). "For example, IL-6 levels in our study had prognostic value similar to that of MR-proADM levels, but IL-6 levels usually exhibit a sudden and transient rather than sustained increase in sepsis, making measurement of this cytokine and its use as a prognostic marker difficult." (PMID 16356231, 2005). "Moreover, a comprehensive study extended this framework to sepsis, demonstrating that the early identification of immune subphenotypes using routinely available biomarkers (e.g., CRP levels, IL-6 levels, and lymphocyte count) could guide more precise immunomodulatory therapy." (PMID 41521316, 2026). "However, another study using an experimentally‐induced sepsis model found that knockout of IL‐6 exerts no significant influence on muscle metabolism compared with wild‐type mice, indicating that IL‐6 might not be the sole trigger for sarcopenia." (PMID 39764565, 2025). "In addition, in a prospective study enrolled of 232 sepsis patients, the AUC of combination of PaO2/FiO2, RAGE, SP-D, AngII and CXCL16 was 0.881 (95% CI: 0.837−0.925), and in Lorraine's research, AUC of multivariable model (includes SPD, RAGE, IL-8, CC16, IL-6) was 0.750 (95% CI: 0.700−0.840)." (PMID 39319361, 2024). "Similarly, the serum TNF‐α and IL‐6 levels were significantly higher in the model group than those in the vehicle group, while the MAF pretreatments (10 and 20 mg/kg) markedly reduced the increased serum TNF‐α and IL‐6 levels in the sepsis mice, and the differences were significant (p < .05)." (PMID 38455195, 2023). "Measurements of IL-6 in the ICU, for both preterm and term infants, are valuable and could be conducted when a child is at an elevated risk of sepsis and shows signs of not being well, especially following major surgeries or as a result of multiple intravenous accesses." (PMID 38255366, 2023).